MMP14 (matrix metallopeptidase 14)
Diseases named in the same sentence as MMP14 in open-access papers (continued):
Sharing a sentence is not in itself a finding about the gene and the disease.
melanoma (continued). "Next, we performed an MMP14 activity assay and observed its higher activity in the case of fibroblasts derived from a culture with metastatic melanoma media in comparison to control cells." (PMID 35538545, 2022). "Elastin fragments enhanced MMP-2 and MMP-14 production by melanoma cells that allowed further melanoma cell invasion through a type I collagen matrix by upregulating MMP-2 expression and activation." (PMID 35008401, 2022). "Studies in vitro investigated the importance of MMP14 in melanoma progression and showed that the increase in collagen XIV in the ECM produced by fibroblasts deprived of MMP14 inhibited proliferation, migration and adhesion of melanoma cells." (PMID 35565234, 2022). "Previous studies have shown the ability of lumican (and its derived peptides), in contrast to decorin (DCN), to inhibit MMP-14 activity in melanoma cells, where lumican directly interacted with MMP-14." (PMID 34885059, 2021). "They found that lymphatic endothelial cells promote melanoma metastasis and invasion by relying on MMP14, NOTCH3, and β1 integrin." (PMID 33748290, 2021). "We showed that increased collagen I and XIV negatively influence melanoma growth in mice when fibroblast-MMP14 is deleted." (PMID 34830157, 2021). "Although MMP14 in melanoma cells has various roles, the functional significance of fibroblast MMP14 shaping the tumor microenvironment is less understood." (PMID 33924099, 2021). "This study shows that loss of fibroblast-MMP14 affects melanoma growth through altering the peritumoral extracellular matrix (ECM) composition, with collagen XIV being a modulator of melanoma progression and a new proteolytic substrate to MMP14." (PMID 34830157, 2021). "MMP14 is expressed in melanomas at the early time point of disease development, and later its expression correlates with disease progression and patient outcome." (PMID 33924099, 2021). "The result that the expression of Mmp-14 increased in our melanoma model suggests promoting the progression of melanoma cells." (PMID 34207144, 2021). "It was reported that lumican inhibits the activity of metalloproteinase MMP-14 and melanoma cell migration in vitro and in vivo." (PMID 33917849, 2021). "Lumican-derived peptides, such as lumcorin (17 amino acids) or L9M (10 amino acids), are able to inhibit the proteolytic activity of MMP-14 and melanoma progression." (PMID 34638415, 2021). "Here, we found that deletion of MMP14 in fibroblasts generates a matrix-rich environment that reduces tumor vascularization and melanoma cell proliferation." (PMID 33924099, 2021). "To confirm that increases in collagen and tissue stiffness levels affect melanoma development in vivo, independently of MMP14 deletion in fibroblasts, we undertook a different in vivo approach." (PMID 33924099, 2021). "We have shown that increased collagen density and tissue tension resulting from MMP14 deletion in fibroblasts leads to melanoma growth inhibition." (PMID 33924099, 2021). "While several studies have demonstrated how MMP14 expression in melanoma cells can contribute to the pathogenesis of melanomas, it is unclear how MMP14 expression in fibroblasts contributes to melanoma progression." (PMID 33924099, 2021). "We investigated extracellular matrix alterations occurring in the MMP14-deleted fibroblasts that can contribute to the modulation of melanoma growth." (PMID 34830157, 2021). "In summary, we show that the fibroblast-specific deletion of MMP14 leads to changes in the peritumoral ECM composition modulating melanoma growth." (PMID 34830157, 2021). "In summary, we show that MMP14 expression in stromal fibroblasts regulates melanoma tumor progression by modifying the peritumoral matrix and point to collagen accumulation as a negative regulator of melanoma." (PMID 33924099, 2021). "To investigate collagen XIV in melanoma, we performed immunostaining in human tissue samples of benign nevi and melanoma and further investigated MMP14 expression." (PMID 34830157, 2021).
melanoma (continued). "The potential anti-metastatic role of lumican in melanoma by inhibiting the membrane type matrix metalloproteinase MMP-14 activity and melanoma cell migration in vitro was also reported." (PMID 33917849, 2021). "In ex vivo invasion assays, melanoma cells formed smaller tumor islands in MMP14Sf−/− skin, indicating that MMP14-dependent matrix accumulation regulates tumor growth." (PMID 33924099, 2021). "In support of its anti-tumor activity, enhanced accumulation of collagen XIV was detected in peritumoral areas of melanoma grown in mice with the fibroblast’s deletion of MMP14." (PMID 34830157, 2021). "To address if changes of the extracellular composition induced by deletion of fibroblast MMP14 are sufficient to affect melanoma growth, we used an ex vivo invasion system." (PMID 33924099, 2021). "The matrix deposited by cultured MMP14-deleted fibroblast displayed an antiproliferative and anti-migratory effect on melanoma cells in vitro." (PMID 34830157, 2021). "We found enhanced expression of collagen XIV around the melanocytic nests of benign nevi with reduced MMP14 expression, whereas around malignant melanomas, collagen XIV was low and MMP14 highly expressed." (PMID 34830157, 2021). "Previous studies from our laboratories showed that MMP-14 activity was inhibited by lumican in melanoma." (PMID 33917849, 2021). "We showed earlier that Snail upregulates the activities of MMP-9 and MMP-14 in B16F1 melanoma cells." (PMID 32629890, 2020). "Collagenolytic enzymes as MMP-13 and MMP-14 are involved in melanoma development where they mediate the vascularization of tumors or tumor cell migration during tissue invasion." (PMID 32906814, 2020). "By binding miR-34a and miR-22 and regulating miR-34a and miR-22 function, MALAT1 up-regulates c-Myc, Met, MMP14, and snail expression, promotes melanoma cell proliferation, invasion, and migration in vitro, and is required for melanoma progression in mice." (PMID 32174966, 2020). "MALAT1 consists of sequence-specific miR-34a- and miR-22-binding sites, binds miR-34a and miR-22, and regulates miR-34a and miR-22 function, leading to up-regulation of c-Myc, Met, MMP14, and snail in melanoma cells." (PMID 32174966, 2020). "Cleavage fragments of the two chain of laminin 332 generated by MMP14 were detected in high invasive melanoma cells and played a crucial role in cell adhesion, migration and vasculogenic mimicry (VM)." (PMID 32392801, 2020). "We also showed previously that extracellularly added Lumican (LUM), that belongs to the family of PGs, inhibits MMP-14 activity induced by Snail in B16F1 melanoma cells." (PMID 32629890, 2020). "Potentiation of MMP-14 activity by Snail was previously observed by us in B16F1 melanoma cells, and this effect was inhibited by Lumican (LUM)." (PMID 32629890, 2020). "Upon tetraspanin CD81 stimulation, MMP14 expression as well as MMP14-dependent melanoma invasion and metastasis are increased through Akt-dependent Sp1 activation, which also support the function of Sp1 in regulating the transcription of MMP14." (PMID 31466240, 2019). "Lumican derived peptides–lumcorin, have been tested against melanoma and show therapeutic potential by inhibiting cell chemotaxis and melanoma growth through MMP-14 inhibition." (PMID 32082161, 2019). "Our results demonstrate that the LEC contact increased MMP14 on the melanoma cell plasma membrane and cell-cell contacts in the metastatic melanoma cell lines." (PMID 29712618, 2018). "MMP14 was recently shown to interact with and activate Notch1 at the cell membrane of melanoma cells, which supported melanoma cell growth." (PMID 29712618, 2018). "These experiments identified proteins called MMP14, Notch3, and β1-integrin as critical to the invasive spread of melanoma cells." (PMID 29712618, 2018). "This suggests that the LEC-induced transient, invasively sprouting phenotype of melanoma cells is mediated by activated Notch3 and β1-integrin both dependent on the key upstream regulator MMP14." (PMID 29712618, 2018).
melanoma (continued). "Membrane type matrix metalloproteinase MMP14 is frequently induced in invasive melanoma and its high expression correlates with melanoma progression and metastasis." (PMID 29712618, 2018). "When melanoma cells with less MMP14 or Notch3 were implanted into zebrafish, the cancer cells spread less efficiently." (PMID 29712618, 2018). "Contrary to what is observed regarding collagen-encoding genes, our present bioinformatics studies further revealed that MMP14 inversely correlates with LUM expression in melanoma, with decreased survival being related to higher MMP14 expression." (PMID 28794454, 2017). "Lgl1 promotes the cell adhesion and inhibites cell migration by downregulating the expression of MMP2 and MMP14, and re-expressing of E-cadherin in melanoma cells." (PMID 26934648, 2016). "Lumican, a small leucine rich proteoglycan, inhibits MMP-14 activity and melanoma cell migration in vitro and in vivo." (PMID 26930497, 2016). "The effect of miR-22 on the invasive and migratory abilities of A375 melanoma cells was also largely abrogated by the MMP14 and Snail plasmids." (PMID 27564100, 2016). "Since malignant melanoma represents one of the deadliest cancer types at the metastatic stage, the aim of the study was to investigate the effect of lumican on MMP-14 activity and migration capacities of Snail overexpressing melanoma cells." (PMID 26930497, 2016). "MiR-22 was decreased and acted as a tumor suppressor in melanoma, and MMP14 and Snail were the functional targets of miR-22." (PMID 27564100, 2016). "While MMP-14 plays a critical role in melanoma progression, its overexpression in colon adenocarcinoma cells was reported to be insufficient to increase experimental liver metastasis of human colon cancer cells." (PMID 26930497, 2016). "We recently showed that the glycosylated form of lumican was able to significantly decrease MMP-14 activity in B16F1 melanoma cells." (PMID 26930497, 2016). "And lastly, we found that MALAT1 promoted melanoma cell growth and metastasis by competitively binding the miR-22, up-regulating MMP14 and Snail, and having downstream effects on MMP2 and E-cadherin protein." (PMID 27564100, 2016). "Histopathological analysis of human tumor samples demonstrated that membrane type metalloproteinase -1 (MMP-14) is expressed in melanoma cells and localized to tumor cells at the invasive front of primary tumors." (PMID 24098450, 2013). "Altogether, we propose two simultaneous mechanisms by which lumcorin is able to inhibit melanoma cell migration: inhibition of phosphorylation of specific proteins and decrease of MMP-14 activity." (PMID 24098450, 2013). "Overexpression of MMP-14 was shown to promote selective invasion and growth of malignant melanoma in vivo." (PMID 24098450, 2013). "Matrix metalloproteinases, especially MMP-2, MMP-9 and MT1-MMP (also named MMP-14), are largely involved in extracellular matrix degradation and melanoma cell migration." (PMID 22539938, 2012). "Our findings suggest that MMP7 and MMP11 may serve as early-stage targets, whereas MMP14 could inform treatment strategies in advanced melanoma and SCC." (PMID 40604111, 2025). "Interestingly, the increased expression of collagen XIV was observed around melanocytic nests of benign lesions with reduced MMP-14 expression, whereas in malignant melanomas collagen XIV was reduced and MMP-14 expression was increased." (PMID 39769318, 2024). "Highly aggressive melanoma cells displayed more prominent effects on the CAFs phenotype in terms of enhanced motility, expressed as an elevated migration and invasion ratio, as well as higher area of digestion in MMP2 and MMP14 proteolytic activity compared to less aggressive melanoma cells." (PMID 36831295, 2023). "In addition, although Mmp-2 and Mmp-9 are known to play important roles in the migration and invasion processes of melanoma, Mmp-14 can activate both." (PMID 34207144, 2021).
melanoma (continued). "We could previously show that deletion of MMP14 in dermal fibroblasts results in the generation of a fibrotic-like skin in which melanoma growth is impaired." (PMID 34830157, 2021). "Collectively, it has been previously reported that lumican, among other functions, effectively regulates cell functional properties, expression of ECM effectors, EMT, invadopodia markers, morphology of invading breast cancer cells, as well as MMP-14 and cell migration in melanoma cells." (PMID 33917849, 2021). "Moreover, the stimulatory effect of SNAIL in the MMP-14 activity and the in vitro melanoma cell migration countered by lumican and its derived peptide in the MMP-14 activity led us to investigate the effect of lumican in vivo." (PMID 33917849, 2021). "Moreover, the potential anti-metastatic role of lumican in melanoma by inhibiting the membrane-type matrix metalloproteinase (MMP)-14 activity and melanoma cell migration in vitro has been studied in vitro and in vivo." (PMID 34572532, 2021). "Using MMP14Sf−/− mice, in which the absence of MMP14 in adult fibroblasts leads to enhanced collagen accumulation and tissue tension, we aimed to investigate the specific role of fibroblast MMP14 and the resulting dermal environmental changes in melanoma growth." (PMID 33924099, 2021). "Additionally, in vivo, we show that independently of MMP14 deletion, a collagen-rich stiff matrix inhibits the growth of melanomas." (PMID 33924099, 2021). "Mechanical intermittent compression with a cycle of 2 h on/2 h off might suppress the invasion ability of melanoma cells by regulating the expression of Mmp-14." (PMID 34207144, 2021). "Thus, the expression of collagen XIV inversely correlates to melanoma progression, and MMP14 expression in these tissues hints at a suppression function for this protein in the transition from benign nevus to malignant melanoma." (PMID 34830157, 2021). "In addition, the gene expression level of Mmp-14, which promotes collagen degradation, correlates with the invasive ability of melanoma cells in collagen gel." (PMID 34207144, 2021). "At the same time, a large number of studies have shown that MMP14 is closely related to the invasion, migration, and angiogenesis of ovarian cancer, gastric cancer, glioma, pancreatic cancer, hepatocellular carcinoma, colon cancer, and melanoma." (PMID 34604053, 2021). "Our MMP14Sf−/− mice model provided us with the great opportunity to directly ask whether loss of MMP14 and the arising resulting collagen-rich stiff ECM promotes or inhibits the growth of melanomas in vivo." (PMID 33924099, 2021). "Additionally, in melanomas, MMP14 is expressed at the leading edge of the invasive front in melanoma and stromal cells in areas of strong MMP2 activation." (PMID 33924099, 2021). "Moreover, previous studies showed the ability of lumican (and its derived peptides), in contrast to decorin, to inhibit MMP-14 activity in melanoma cells, where lumican directly interacts with MMP-14 and inhibits its activity." (PMID 32548117, 2020). "We also investigated the correlation of the seven prognostic-associated TBCs between MMP-related genes (MMP2, MMP9, MMP7, MMP14, BSG, EGFR, MMP1, MMP3) and EMT-associated genes (TWIST1, VIM, CDH2, ACTA2, ZEB1), which also indicated a central role of TBCs in melanoma." (PMID 33194704, 2020). "In addition, both β1-integrin activation and Notch3 expression depend on the MMP14 relocalization to the plasma membrane in melanoma cells upon contact with lymphatic endothelial cells, which triggers an enhanced 3D invasive sprouting of the tumor cells." (PMID 31466240, 2019). "MMP14 is required for the increased sprouting growth of LEC primed melanoma cells in 3D." (PMID 29712618, 2018). "Notably, the expansively growing metastatic melanoma cells adopted an invasively sprouting phenotype in 3D matrix that was dependent on MMP14, Notch3 and β1-integrin." (PMID 29712618, 2018).
melanoma (continued). "Importantly, the interaction of these melanoma cells with LECs led to significantly increased metastasis of melanoma xenografts in vivo, which was dependent on MMP14 and Notch3." (PMID 29712618, 2018). "A lumican-based strategy targeting Snail-induced MMP-14 activity might be useful for melanoma treatment." (PMID 26930497, 2016). "MMP-14 is not or low expressed in majority of normal tissues, but widely expressed and critical to the acquisition of the invasive and metastatic phenotype of prostate, breast, melanoma and ovarian carcinomas; therefore, targeting MMP-14 is an effective approach to cancer therapy." (PMID 26314845, 2015). "Therefore, the decreased FAK phosphorylation and the inhibition of MMP-14 activity induced by lumican in melanoma cells might explain, at least in part, the anti-invasive effect of this SLRP." (PMID 33917849, 2021). "However, it is unclear whether this is the direct consequence of deletion of MMP14 or whether an environment with high collagen, matrix density, and altered mechanics levels would be sufficient to inhibit melanoma growth." (PMID 33924099, 2021). "Thus, a lumican-based strategy targeting the Snail-induced MMP-14 activity might be helpful for melanoma treatment." (PMID 34572532, 2021). "Thus, Mmp-14 is a critical factor in the progression process of melanoma." (PMID 34207144, 2021). "Notably, CD45+ cells infiltrating BrM in a spontaneous melanoma model also expressed MMP14 (available online), confirming that the MMP14 promoter is also active in BrM-infiltrating hematopoietic cells in a more physiological model and in the absence of irradiation." (PMID 31501884, 2020). "Therefore, we investigated whether LEC priming would induce changes in MMP14 expression in melanoma cells." (PMID 29712618, 2018). "Therefore, the decreased FAK phosphorylation and the inhibition of MMP-14 activity induced by lumcorin in melanoma cells might explain, at least in part, the anti-migratory effect of this peptide." (PMID 24098450, 2013). "Extensive research has been concentrated on identifying and developing MMP inhibitors for cancer treatment, including melanoma, with particular focus on MMP‐2, MMP‐9 and MMP‐14." (PMID 41546170, 2026). "MMP-14, in particular, is known to activate MMP-2, enhancing the invasive potential of melanoma cells." (PMID 40604111, 2025). "Although this study does not directly investigate the degradative axis, previous work in melanoma models has shown that CSPG4 can facilitate cell invasion through activation of membrane-bound MMP complexes, potentially including MMP-14, at the cell surface." (PMID 40724839, 2025). "STRING-based analysis showed that MMP7, MMP11, and MMP14 formed dense interaction networks with other ECM-related genes, indicating their regulatory significance in SCC and melanoma progression." (PMID 40604111, 2025). "A possible similar activation of keratinocytes surrounding melanoma has been suggested by in vitro evidence that medium conditioned by melanoma cells stimulates the production of MMP3, MMP9, and MMP14 by Hacat cells while lowering TIMP expression." (PMID 38473275, 2024). "LUM inhibits snail-induced melanoma migration by blocking MMP-14 activity, inhibits B16F1 melanoma cell lung metastasis and also inhibits prostate cancer development." (PMID 38474072, 2024). "Phosphoinositide 3-kinase elevates the level of matrix metalloproteinase-14 (MMP-14) in aggressive cells; MMP-14 in turn activates MMP-2, which in turn activates the secretion of γ2′ and γ2x pro-migratory fragments leading to VM in melanomas." (PMID 36776217, 2023). "To explore the functional consequence of stromal MMP14 and dysregulated ECM composition in melanoma growth, we used this mouse strain as an in vivo model for melanoma growth." (PMID 33924099, 2021). "Membrane type-1 MMP (MT1-MMP) (or MMP-14) is a cell–surface membrane protein, which activates MMP-2 leading to matrix degradation and melanoma cell invasion and metastasis." (PMID 34207884, 2021).